BMP3 (bone morphogenetic protein 3)
Diseases named in the same sentence as BMP3 in open-access papers (continued):
Sharing a sentence is not in itself a finding about the gene and the disease.
pancreatic adenocarcinoma (3 papers, 2016 to 2023). "We also showed that hypermethylation of BMP3 was associated with decreased survival in stage IV pancreatic adenocarcinoma." (PMID 29212200, 2017). "Initially, analysis of pancreatic adenocarcinoma TCGA data confirmed that the methylation levels of BMP3, NPTX2, SPARC, SFRP1 and TFPI2 genes were significantly higher in tumor compared with normal tissue, reinforcing their potential as useful biomarkers." (PMID 37481552, 2023). "To our knowledge, we are the first to describe a prognostic value of BMP3 hypermethylation with regard to stage IV pancreatic adenocarcinoma." (PMID 29212200, 2017). "We developed a diagnostic prediction model (age >65, BMP3, RASSF1A, BNC1, MESTv2, TFPI2, APC, SFRP1 and SFRP2), which was able to differentiate between pancreatic adenocarcinoma and a large control group of great clinical relevance." (PMID 27891190, 2016). "A panel of hypermethylated genes (BMP3, RASSF1A, BNC1, MESTv2, TFPI2, APC, SFRP1 and SFRP2) are able to differentiate between patients with pancreatic adenocarcinoma and a most relevant control group." (PMID 27891190, 2016).
prostate carcinoma (3 papers, 2017 to 2023). A carcinoma that arises from epithelial cells of the prostate gland. "We found that BMP inhibition in lytic‐like prostate cancer cell lines increases the transcription of BMP3 in some of the cell lines." (PMID 36054271, 2023). "This alternative BMP3 response could explain the many ways that prostate cancer induced bone disease creates a unique bone matrix environment that is not a full recapitulation of a healthy osteogenesis program." (PMID 36054271, 2023). "Across all three lytic‐like human prostate cancer cell lines, BMP inhibition resulted in decreased MMP8 and increased BMP3 gene expression." (PMID 36054271, 2023). "Specifically, the expression of BMP-3 and BMP-5 was relatively higher whereas the expression of BMP-7 was comparatively lower in prostate cancer tissue than normal tissue." (PMID 31137764, 2019). "CRISPR/Cas9 editing of PC-3 cells showed impaired ligand-stimulated expression of MMP9, VEGF, BMP3, PSA, RUNX2, and OCN, which are involved in prostate cancer progression." (PMID 28659174, 2017).
diabetes (2 papers, 2018 to 2024). "Other genes encode proteins involved in calcium handling (BMP3 and SYNDIG1) or are associated with diabetes mellitus (GLIS3 and TRIB3), suggesting a potential link to accelerated atherosclerosis development." (PMID 38725839, 2024).
fibrosis (2 papers, 2017 to 2021). the formation of excess fibrous connective tissue in an organ or tissue in a reparative or reactive process. "Similarly, in the present study, a mutually inhibitory relationship between TGF-β1 and BMP3 was observed in both human patients and a murine fibrosis model." (PMID 29113323, 2017). "Interestingly, in our study, both BMP3 and TGFB2 expressions were increased in the severe fibrosis group and correlated positively with the degree of fibrosis in LSGs from SS patients." (PMID 34400910, 2021).
glioma (2 papers, 2018 to 2021). A benign or malignant brain and spinal cord tumor that arises from glial cells (astrocytes, oligodendrocytes, ependymal cells). "This whole genome variant association approach successfully replicated two previously identified loci that were known to be fixed within the screw tails breeds namely the BMP3 missense mutation (CFA32) associated with head morphology and the glioma susceptibility locus (CFA26)." (PMID 30521570, 2018). "For instance, the TGF-β signaling pathway was found to be altered through glioma progression, as observed by an increase in the level of BMP molecules, including BMP3 and BMP4, as well as their targets, such as Smad1/5/8 and Id." (PMID 33671331, 2021).
lung fibrosis (2 papers, 2017 to 2022). "In human lung tissue, BMP3 serves as a prognostic tool to predict the level of lung fibrosis and patient survival rate, but the mechanism by which it regulates myofibroblast differentiation was not described." (PMID 35879352, 2022). "Quantification of Western blots showed that BMP3 expression and the degree of pulmonary fibrosis were inversely correlated." (PMID 29113323, 2017). "In this study, we aimed to investigate the potential role of BMP3 playing in pulmonary fibrosis from clinical diagnosis to molecular signaling regulation." (PMID 29113323, 2017). "The role of BMP3 in the pathogenesis of pulmonary fibrosis in vivo was determined using a bleomycin–induced murine pulmonary fibrosis model The bleomycin animal model is widely used in the assessment of potential antifibrotic agents." (PMID 29113323, 2017). "The function of BMP3 was investigated in both fibroblast cells and a bleomycin-induced murine pulmonary fibrosis model." (PMID 29113323, 2017). "Up-regulation of BMP3 prevented pulmonary fibrosis processing through inhibiting cellular proliferation of fibroblasts as well as TGF-β1 signal transduction." (PMID 29113323, 2017). "BMP3 suppresses TGFβ1-induced myofibroblast differentiation in murine pulmonary fibrosis models." (PMID 35879352, 2022). "We also showed that BMP3 could suppress the fibrotic process of pulmonary fibrosis both in vivo and in vitro." (PMID 29113323, 2017). "Finally, our results uncovered an antagonistic relationship between BMP3 and TGF-β1, which played a critical role in the pathogenesis of pulmonary fibrosis in BLM." (PMID 29113323, 2017). "To determine whether BMP3 is a novel factor involved in the pathogenesis of IPF and INSIP as well as a potential new therapeutic target, we established a murine pulmonary fibrosis model based on bleomycin treatment." (PMID 29113323, 2017). "Taken together, our results suggested that the low expression level of BMP3 may indicate the unfavorable prognosis of IPF patients, targeting BMP3 may represent a novel potential therapeutic method for pulmonary fibrosis management." (PMID 29113323, 2017). "Bone morphogenetic protein 3 (BMP3) is a member of the transforming growth factor-β (TGF-β) super-family, which has not been implicated in pulmonary fibrosis previously." (PMID 29113323, 2017). "Since BMP3 has not been previously reported to be involved in IIPs, an extensive series of in vivo and in vitro studies were carried out using the bleomycin-induced pulmonary fibrosis animal model." (PMID 29113323, 2017). "Taken together, these results suggested that BMP3 may alleviate the fibrotic processing by suppressing the activation of TGF-β1 signaling pathway and that the mutually antagonistic relationship between BMP3 and TGF-β1 plays a crucial role in the pathogenesis of pulmonary fibrosis." (PMID 29113323, 2017).
lung squamous cell carcinoma (2 papers, 2012 to 2022). "In 2015, researchers from Huazhong University of Science and Technology conducted transcriptomics level analyses on human lung squamous cell carcinoma, confirming the driver role of BMP3 and BMP5 at the transcriptomics levels." (PMID 35155435, 2022).
Arthritis (1 paper, 2020). Inflammation of a joint. "Correspondingly, induction of BMP3 overexpression through intra-articular injection of ad-BMP3 diminished arthritis severity in AIA rats." (PMID 32568738, 2020). "More importantly, inflammatory cells infiltration, arthritis scores, and paw swelling were significantly decreased by intra-articular injection of ad-BMP3 in AIA knees in vivo." (PMID 32568738, 2020). "Thus, our results confirm that overexpression of BMP3 induced by intra-articular injection of ad-BMP3 alleviates arthritis severity in AIA rats." (PMID 32568738, 2020).
Autoimmunity (1 paper, 2022). The occurrence of an immune reaction against the organism's own cells or tissues. "Both NK activation and autoimmunity are linked to BMP signaling, e.g., via an autocrine activation pathway via BMP receptors and BMP ligands in NK cells, which fits our identified target genes BMP1, BMP2, BMP3, BMP7, BMP6, BMPER, BMPR1B, and, most importantly, BMPR2." (PMID 35455956, 2022).
dysplasia (1 paper, 2023). A usually neoplastic transformation of the cell, associated with altered architectural tissue patterns. "BMP3 and SOST are potential biomarkers for IBD with dysplasia or CAC and axial SpA/IBD, respectively; however, other BMP-relevant molecules may also have the potential to be novel biomarkers in IBD patients." (PMID 37391444, 2023). "Additionally, in a study done by Johnson at a single centre in 2 blinded phases, BMP3 methylation was higher in mucosae and stool from 29 IBD patients with dysplasia compared to that of 44 matched IBD controls." (PMID 37391444, 2023). "In a prospective blinded study carried out by Kisiel, buffered stool-extracted DNA from 19 IBD cases with dysplasia or CAC and 35 IBD controls without dysplasia or CAC were analysed; BMP3 showed a high association in stools for dysplasia and CAC." (PMID 37391444, 2023).
glaucoma (1 paper, 2024). Increased pressure in the eyeball due to obstruction of the outflow of aqueous humor. "In this study, the SNPs with high OR values for cataract exposure on glaucoma were ZNF800 (rs62621812 with OR = 1.213), LOC338694;MYEOV (rs79721202 with OR = 1.144), BMP3 (rs72868578 with OR = 1.131), SOX2-OT (rs9823623 with OR = 1.093), and BET1L (rs11245997 with OR = 1.085)." (PMID 38674349, 2024).
inflammatory bowel disease (1 paper, 2023). A spectrum of small and large bowel inflammatory diseases of unknown etiology. "Indeed, inflammatory bowel disease (IBD) increases the risk of colorectal cancer when methyl groups are covalently bound to cytosines in the CpG islands in stool DNA, specifically in loci containing BMP3, VIM, EYA4 and DRG4 genes." (PMID 38299096, 2023).
lung carcinoma (1 paper, 2022). "Apart from HAND1, BMP3 together with BMP5 has been considered potential multi-omics level lung cancer biomarkers according to recent publications." (PMID 35155435, 2022).
myocarditis (1 paper, 2024). Myocarditis is a condition that is characterized by inflammation of the heart muscle (myocardium). "These regions localized to Bone Morphogenetic Protein 3 (BMP3) and Leucine-Rich Repeat Containing 4 C (LRRC4C), suggesting a potential connection between these genomic regions and vaccine-related myocarditis." (PMID 38844841, 2024).
non-small cell lung carcinoma (1 paper, 2009). A group of at least three distinct histological types of lung cancer, including non-small cell squamous cell carcinoma, adenocarcinoma, and large cell carcinoma. "Concurrent epigenetic inactivation of BMP3 and BMP6 was shown to be associated with the hyperactivation of the RAS-RAF-MEK-ERK signaling pathway in non-small-cell lung cancer." (PMID 20027224, 2009).
renal fibrosis (1 paper, 2022). A final common manifestation of a wide variety of chronic kidney diseases characterized by glomerulosclerosis and tubulointerstitial fibrosis. "Additionally, Bmp1-3 can accelerate renal fibrosis in the mouse model of CKD by increasing the deposition of ECM attenuated by polyclonal antibodies specifically against Bmp1 or Bmp3." (PMID 36523757, 2022).
vision disorder (1 paper, 2023). Any impairment to the vision. "Among the novel GWAS-identified associations with AL, our study revealed potential candidate genes, including SLC25A12, BMP3, RGR, RBFOX1, and MYO5B, which have all been linked to visual function or eye development and have been implicated in vision disorders." (PMID 37351342, 2023).
tumor (20 papers, 2005 to 2024). "Given the evidence for a tumor suppressor role for BMP3 in other cancer types, we hypothesized that inactivation of BMP3 expression in biliary cancer cell lines would be associated with increased cell proliferation and viability." (PMID 25077038, 2013). "Our group recently demonstrated higher DNA methylation levels for both SEPT9 and BMP3 genes in CRC tumor tissue compared to normal tissue in a Brazilian population." (PMID 37338022, 2023). "BMP3 acts as a tumor suppressor in colon cancer and has also been found methylated in some types of stomach, breast and lung cancer." (PMID 35625579, 2022). "The size of the tumor also affected the expression of BMP3 (P = 0.0047), BMP7 (P = 0.0210), BMPR1B (P = 0.0460), ACVR2A (P = 0.0350), ACVRL1 (P = 0.0045), TGFBR2 (P = 0.0170), and TGFBR3 (P = 0.0150) according to the K-W test." (PMID 34036102, 2021). "In contrast, drastic increases in weights and volumes of KM12-BMP3-shRNA tumors were observed compared to their matching controls, exhibiting again the tumor-enhancing effects of BMP3 knockdown." (PMID 31665064, 2019). "Further histological examination of the tumor xenografts from SCID mice revealed a much higher degree of BMP3 expression in HCT116-BMP3 tumor cells, resulting in decreased Ki67 staining." (PMID 31665064, 2019). "From these results, we can conclude that BMP3 can strongly inhibit tumor formation and growth in vivo." (PMID 31665064, 2019). "Then, we demonstrated that BMP3 displayed its tumor-suppressive effects in CRC both in vitro and in vivo systems." (PMID 31665064, 2019). "We aimed to quantitatively assess BMP3 methylation in resected CC tumor specimens using methylation specific PCR and evaluate the tumor suppressor role of BMP3 in biliary cancer cell lines in comparison to an immortalized normal cholangiocyte cell line." (PMID 25077038, 2013). "BMP3 expression therefore exerts a profound tumor suppressive effect on the Mz-ChA-1 biliary cancer cell line." (PMID 25077038, 2013). "In primary CC tumor tissue specimens significantly more methylated BMP3 copies were found when compared to matched benign bile duct epithelium from the same patient, with high specificity." (PMID 25077038, 2013). "Further, forced re-expression of BMP3 led to suppression of colony formation, supporting a tumor suppressor function for BMP3." (PMID 25077038, 2013). "First, we identified BMP3 as a potential tumor suppressor in CRC." (PMID 31665064, 2019). "Our study reveals a previously unknown mechanism of BMP3 tumor suppression in CRC and provides a rationale for future investigation of BMP3 as a potential target for the development of novel therapeutic agents to fight CRC." (PMID 31665064, 2019). "Both genes have been previously shown to inhibit CRCs and may play tumor suppressor roles in HCT116 cells with stably expressed BMP3." (PMID 31665064, 2019). "Our data strongly support a tumor suppressor role for BMP3 in biliary cancers." (PMID 25077038, 2013). "This is the first report of a tumor suppressor function of BMP3 in biliary cancer cell lines." (PMID 25077038, 2013). "In conclusion, our study reveals a previously unknown mechanism of BMP3 tumor suppression in CRC." (PMID 31665064, 2019). "In tumor suppressor genes such as O6-methyguanine-DNA methyl transferase (MGMT), bone morphogenetic protein 3 (BMP3), and EFHD1 (EF-hand domain family member D1), methylation at certain CpG sites results in gene suppression and the formation of malignancy." (PMID 38380073, 2024). "Among 11 BMPs, BMP3 and BMP8A expression levels were upregulated, and 5 BMPs (BMP2, BMP5, GDF5, BMP6, and GDF10) downregulated in tumor tissues compared with normal tissues." (PMID 34745928, 2021). "In the present study, three BMPs members belonging to the Transforming growth factor beta (TGF-β) superfamily, namely BMP3, BMP4 and BMP7, were found hyper-methylated in cDLBCL, supporting the role of BMP families as tumor suppressor genes." (PMID 28912427, 2017).
tumor (continued). "In resected CC tumor samples, we found a significantly greater number of methylated BMP3 copies when compared to matched, non-malignant bile duct samples." (PMID 25077038, 2013). "While CC tumor samples contain a significantly greater number of copies of methylated BMP3 than benign bile duct tissues, the sensitivity was not high enough to support the use of BMP3 as a single diagnostic marker for CC." (PMID 25077038, 2013). "Likewise, for the BMP3 gene in the AA + CRC versus control model, the AUC was 0.562, and the optimal cutoff value for methylation status was 0.16%, resulting in 45% sensitivity and 62% specificity in the detection of advanced neoplasia (AA + CRC)." (PMID 37338022, 2023). "We therefore hypothesized that BMP3 expression may be reduced in biliary cancers, resulting in a lack of tumor suppressor function due to aberrant BMP3 promoter methylation, and that methylated BMP3 may serve as a clinically useful biomarker in these cancers." (PMID 25077038, 2013). "The methylation status of SEPT9, BMP3, NDRG4, and SDC2 was analyzed by using qMSP in matched patient tissue samples (n=23) from tumor, non-tumor adjacent tissue, and normal tissue." (PMID 31602277, 2019). "The eight probes extracted from the RFECV method showing discriminative power between tumour and nontumour samples included cg17105014 (GYPC), cg23273897 (MME), cg22083047 (PRICKLE2), cg09396217 (ANGPT1), cg01049530 (BMP3), cg18237405 (CPNE5), cg12741420 (IRF4) and cg11754206 (KCNB2)." (PMID 36779430, 2023).
cancer (17 papers, 2012 to 2024). A tumor composed of atypical neoplastic, often pleomorphic cells that invade other tissues. "Genes often found to be epigenetically silenced or with low expression levels in ovarian or other cancers (Adora1, Bmp3, Ccl6, Ephx2, Lefty2, Pf4, Socs2) were downregulated by MOSE-LTICv in the OFB." (PMID 38264656, 2023). "The apparent strength in association suggests the relation between vitamin D and the BMP3 gene, plus the anti-cancer effect of vitamin D in GC via suppression of BMP3 methylation." (PMID 34722053, 2021). "BMP3 had a considerably low detection rate in all clinical samples, with only 6 positive cases detected out of 180 cancer samples." (PMID 34621892, 2021). "The only downregulated gene found was BMP3, though, interestingly, this gene has been found downregulated in cancers." (PMID 33671464, 2021). "Bone Morphogenetic Protein 3 (BMP3) has been shown to be methylated in cancers of the colorectum, pancreas, stomach, lung and breast, but has not been reported in biliary cancers." (PMID 25077038, 2013). "Alterations in BMP3 expression are found in a variety of cancers, indicating that BMP3 may have other roles besides regulating bone formation." (PMID 35054971, 2022).
infection (4 papers, 2019 to 2024). The state of being infected such as from the introduction of a foreign agent such as serum, vaccine, antigenic substance or organism. "Bcgbl1 mutants had reduced phosphorylation levels of two MAPKs, namely Bmp1 and Bmp3, thereby reducing infection." (PMID 38048363, 2023). "HCT116 and KM12 cells infected lentivirus carrying BMP3 coding sequence or BMP3 shRNA were used as the cell models and efficiency of infection was tested by WB and q-PCR." (PMID 31665064, 2019). "Additionally, infection with C. parvum resulted in downregulation of a number of genes, including some involved in intestinal differentiation pathways, such as ATOH1 or BMP3." (PMID 38189373, 2024).
Cardiovascular disease (1 paper, 2024). "Among these, 10 regions, proximal to or within the genes OVAAL, BMP3, RIOK1, AC096553.5, MCPH1, KCNU1, GLIS3, TUT7, TRIB3, and SYNDIG1, represent novel associations with MI and have not been previously linked to Cardiovascular disease (CVD)-related traits." (PMID 38725839, 2024).
skeletal diseases (1 paper, 2025). "Collectively, our results indicate that BMP3 plays an important role in bone formation, exhibiting both inhibitory and regulatory properties in the context of ectopic bone formation, which may have important implications for therapeutic strategies in bone regeneration and skeletal diseases." (PMID 41153791, 2025).